OR2Y1 (olfactory receptor family 2 subfamily Y member 1)
Description:
Odorant receptor.
Synonyms: OR5-2
Tractability: Antibody: UniProt places it where antibodies can reach, with medium confidence; UniProt predicts a signal peptide or a membrane-spanning region; its Gene Ontology location is reachable by antibodies, with medium confidence.
Gene: Protein-coding gene on chromosome 5 (180,739,123 to 180,740,058, reverse strand). Ensembl gene ENSG00000174339.
Subcellular location: Cell membrane
Pathways (Reactome):
Sensory Perception: Expression and translocation of olfactory receptors
Gene Ontology:
Molecular function: olfactory receptor activity; G protein-coupled receptor activity
Biological process: detection of chemical stimulus involved in sensory perception of smell; G protein-coupled receptor signaling pathway
Cellular component: plasma membrane; membrane
Genetic constraint (gnomAD): Loss-of-function variants: 0 observed, 0.26 expected, observed/expected ratio (o/e) 0, 90% interval 0 to 1.87. That is too few expected variants to judge how well the gene tolerates losing a copy. Missense variants: 412 observed, 409.77 expected, observed/expected ratio (o/e) 1.01, 90% interval 0.93 to 1.09. Synonymous variants: 161 observed, 162.46 expected, observed/expected ratio (o/e) 0.99, 90% interval 0.87 to 1.13.
Homologues: Orthologues: chimpanzee OR2Y1 (98% identical), macaque OR2Y1 (95% identical), guinea pig OR2Y1 (82% identical), mouse Or2y1d (80% identical), mouse Or2y16 (79% identical), rat Or2y1d (79% identical), mouse Or2y15 (79% identical), rat Or2y15 (78% identical), rat Or2y16 (77% identical). Paralogues in human: OR2G3 (59% identical), OR2G6 (59% identical), OR2B2 (57% identical), OR2C1 (56% identical), OR2W3 (55% identical), OR2C3 (55% identical), OR2G2 (55% identical), OR2I1 (55% identical), OR2J2 (55% identical), OR2J3 (55% identical), OR2B6 (55% identical), OR2J1 (54% identical), and 80 more.